LEP (leptin)
Diseases named in the same sentence as LEP in open-access papers (continued):
Sharing a sentence is not in itself a finding about the gene and the disease.
cancer (continued). "Our group and others have shown that during leptin-induced EMT of MCF10A cells, and in several cancer cell lines, this hormone promotes the formation of stress fibers." (PMID 31554180, 2019). "Several recent reviews, such as, discuss oncogenic roles of leptin, including maintenance of TIC properties, in various types of cancer." (PMID 29361779, 2018). "JAK/STAT3 is a major signalling pathway for leptin action and JAK/STAT3 can be a signalling intermediate for EMT via TGFB1 in cancer." (PMID 28542577, 2017). "We further included the 9 known cancer-signaling pathways from the NetPath database, namely, EGFR1, FSH, IL-1, IL-4, IL-5, Leptin, RANKL, TNF-alpha, and TSH." (PMID 29190299, 2017). "In addition, leptin acting via the OB-R may regulate the migration of cancer cells." (PMID 28750624, 2017). "For example, cancer cells stimulate expression of adipokines and adipocytokines (including IL-6, IL-1β, CCL2, CCL5, TNF-α, MCP-1, leptin), proteases, and inhibitors (e.g., MMP-11, PAI-1)." (PMID 28101337, 2017). "Among these active biological molecules, leptin and secreted phospholipase A2-IIA (sPLA2-IIA, sPLA2) have been found elevated in obese individuals and some forms of cancer." (PMID 28249041, 2017). "Leptin is able to bind to the leptin receptor (ObR) and then activates the intracellular JAK/STAT, MAPK/ERK1/2 and PI3K/AKT pathways, promoting cancer progression." (PMID 28415788, 2017). "Further studies will be needed to gain more insights into the mechanisms by which leptin and estrogen receptor induces activation of AMPK signaling in cancer cells." (PMID 29312618, 2017). "Leptin is known to activate a number of different signaling pathways, particularly the JAK2/STAT3 pathway, including in cancer cells." (PMID 29212170, 2017). "LEP combines to LEPR and exerts its important roles in the development of metabolic disorders and malignancies." (PMID 29312594, 2017). "In cancer cells, the expression of ER gene and protein in COV434 and KGN cells was unchanged by the addition of leptin." (PMID 28861689, 2017). "Consequently, a total of 11 studies were enrolled in the meta-analysis investigating the relationships between LEP/LEPR/ADIPOQ/ADIPOR1/ADIPOR2 variants and total PCa risk, and ten studies were included in the pooled-review discussing these polymorphisms' impact on the aggressiveness of cancer." (PMID 27768592, 2016). "In particular, adipocytes produce insulin-like growth factors, which are known to have cancer-promoting effects on renal cells and multiple angiogenic factors including VEGF and leptin." (PMID 27532115, 2016). "Leptin activation of JAK/STAT and other canonic pathways induce several processes involved in cancer." (PMID 27472371, 2016). "Leptin, a 16-kDa nonglycosylated protein encoded by the Ob gene and mainly secreted by adipose tissue, is a protein hormone with relevant roles in cell survival, differentiation, inflammation and angiogenesis which indicate its potential activities in cancer development and progression." (PMID 27185268, 2016). "Inhibition of leptin STAT3 signaling, achieved by administration of leptin antagonists, by leptin receptor monoclonal antibodies, or by upregulating SOCS3 would facilitate apoptosis and impede cancer cell growth." (PMID 26982332, 2016). "Therefore, leptin/OB-R signaling could be an attractive target for cancer prevention and therapy." (PMID 27472371, 2016). "Adiponectin also inhibits leptin-induced metastasis by downregulating JAK/STAT3 pathway, displaying an inverse correlation with cancer development." (PMID 27119501, 2016). "In this review, we will discuss the specific relationship between leptin-JAK-STAT signaling and cancer." (PMID 27472371, 2016). "The mechanism of action in cancer cachexia is not well understood but is likely related to the inhibition of IL-1, TNF-α, and leptin as well as the stimulation of NPY (Plata-Salamán, 1991)." (PMID 24624094, 2014).
cancer (continued). "Recent evidence suggests that in cancer cachexia IL-1 and TNF-α mimic leptin signaling and interfere with the orexigenic response to reduced leptin levels." (PMID 24624094, 2014). "Binding of leptin to its receptor LEPR-Long elicits a proliferative and angiogenic signal transduction cascade, which varies remarkably depending on cancer cell types." (PMID 25482303, 2014). "Age at diagnosis, BMI, serum leptin and prostate specific antigen (PSA) levels, and combined Gleason grade in subjects with cancer were similar between prostatic disease groups (P >0.05 for all comparisons)." (PMID 23009291, 2012). "It has since been confirmed that leptin increases migration through the MAPK and PI3K pathways in prostate, liver, cartilage, and breast cancers, as well as the JAK-STAT pathway in colon, prostate, liver, and breast cancers." (PMID 22263109, 2012). "The decrease in leptin:adiponectin ratios in MOD-1 and SPI-HF-fed WT mice, compared to CAS-HF- fed WT mice, further substantiates the linkage between the cancer-preventive effects of SPI consumption and reduction in ME1 expression." (PMID 23056418, 2012). "The role of leptin signaling in the regulation of VEGF and VEGFR2 by MCF-7 and MDA-MB231 cancer cells was further studied in vitro." (PMID 19531256, 2009). "Both functional studies and genetic analyses have highlighted the role of LEP and LEPR in cancer pathogenesis and disease progression." (PMID 16504019, 2006). "In the same study, while a high serum leptin level was demonstrated as an independent factor for PFS (p = 0.0406), the associations between leptin-R expression status and cancer-related survival and PFS times were not significantly different." (PMID 41010935, 2025). "In fact, although there are no direct studies linking IF to reduced cancer risk in humans, its effect has been explored through its impact on tumor-related factors, such as insulin, glucose, IGF-1, leptin levels, adiponectin and weight loss." (PMID 39940361, 2025). "Leptin treatments are not currently applied in cancer, since some data suggests a dual role of leptin in carcinogenesis." (PMID 40227577, 2025). "In patients with inflammatory diseases (e.g., cancer), leptin levels are typically low; however, they do not increase appetite because of hypothalamic disorders and excess proinflammatory cytokines." (PMID 41373996, 2025). "The release of adipokines, such as leptin and adiponectin, further influences tumor biology; leptin, often elevated in high VAT, can promote cancer cell proliferation and migration, whereas adiponectin, which tends to be lower in visceral obesity, has anti-inflammatory and antiproliferative effects." (PMID 40500581, 2025). "It is hypothesized that a FMD may promote cancer prevention in mouse models by reducing levels of IGF-1, insulin, leptin, glucose, visceral fat, and other disease and aging markers." (PMID 39940361, 2025). "MSC-mediated protection against apoptosis has been reported in other cancer types and is often attributed to the secretion of anti-apoptotic cytokines such as insulin-like growth factor 1 (IGF1) and leptin, or via exosome-mediated delivery of survival signals such as miR-410, miR-21 and miR-34a." (PMID 40940728, 2025). "Both metabolic dysfunction and cancer are characterized by changes in circulating factors, such as fibroblast growth factor 21 (FGF21), growth differentiating factor 15 (GDF‐15), leptin and inflammatory cytokines." (PMID 40237521, 2025). "Moreover, adipose tissue secretes various adipokines, including tumor necrosis factor (TNF)-α, interleukin (IL)−6, leptin, and insulin-like growth factor (IGF-1), which are thought to have pathological effects in various cancers." (PMID 40624408, 2025). "Leptin also induces lymphocyte Treg differentiation and increases secretion of pro-inflammatory interleukin 6 (IL-6) and tumor necrosis factor α (TNF-α) by monocytes, which is crucial for cancer progression." (PMID 40076482, 2025).
cancer (continued). "Studies have shown that leptin levels are significantly reduced in cachectic cancer patients compared to healthy, non-cachectic individuals." (PMID 41373779, 2025). "While not directly relevant to angiogenesis in cancer, these studies indicate that pharmacological agents can interrupt the leptin signaling axis in vascular disease." (PMID 39439572, 2024). "In mouse models, the FMD synergistically improved the cancer-fighting impact of endocrine therapies, such as tamoxifen and fulvestrant, by significantly lowering systemic levels of IGF-1, insulin, and leptin, and impeding AKT–mTOR signaling pathways through the increased expression of EGR1 and PTEN." (PMID 38321992, 2024). "Excess body fatness is linked to elevated levels of hormones and substances from fat cells that promote inflammation, such as leptin, TNF-α, and IL-6, which could potentially stimulate the growth of cancer cells." (PMID 39317703, 2024). "Leptin, via SOCS-STAT3 transcription activation, activates many downstream signaling pathways, such as MAPK and AKT pathways, resulting in increased angiogenesis, proliferation, decreased cancer cell death, and therapeutic resistance." (PMID 39040042, 2024). "In patients with cancer, leptin also correlates with indices of adiposity, but unlike in healthy individuals, is positively associated with appetite." (PMID 38481033, 2024). "Furthermore, leptin was reported to promote epithelial-to-mesenchymal transition (EMT) and cancer stem cell enrichment." (PMID 39040042, 2024). "Nonetheless, the roles of cellular energy metabolism in leptin-induced pro-cancer processes are not fully established." (PMID 39609706, 2024). "The expression of the key adipokines adiponectin, adipisin, leptin, resistin, and visfatin were significantly decreased by the cancer cells irrespective of the diet in the OFB, but not in the other adipose tissues." (PMID 38264656, 2023). "In addition, we observed the expression dysregulations of NLRX1, AKT1, CSRP1, LEP, MUC4 and SEMA4B in cancer tissues by immunohistochemistry." (PMID 36817485, 2023). "Evaluation studies show new insights concerning Ras/MAPK hyperactivation as a shared pathway, promising endocrine and homeostatic approaches, such as energy homeostasis (e.g. by leptin and insulin), calcium homeostasis and future treatments from the field of RAS-driven cancers." (PMID 37480127, 2023). "In a large European prospective study and different variable matching models, neither leptin nor its receptor serum levels (sOB-R) were associated with rectal and overall CRC cancers." (PMID 37942199, 2023). "Leptin, ferritin, FGF2, and prolactin may potentiate cancer stem cell formation; ferritin also impacts pathways leading to the EMT transition." (PMID 37857666, 2023). "With respect to colorectal cancer, immunohistochemical measures of leptin were used to accurately predict the cancer prognosis, independent of other indicators." (PMID 35628271, 2022). "Adipose tissue dysregulation promotes an inflammatory state in which adipocytes and immune cells release pro-inflammatory cytokines and sex hormones, such as hs-CRP, IL-6, leptin, TNF-α, estrogens, among others, increasing cell proliferation and cancer development." (PMID 35795051, 2022). "Leptin was found to activate MAPK, Jak/Stat, and PI3K/AKT pathways, thus promoting oncogenic signalling, angiogenesis, and immunomodulation, leading to the enhanced proliferation and survival of cancer cells." (PMID 35328822, 2022). "Mechanistically, leptin binds its receptor OB-R in CSCs by promoting activation of the JAK/STAT3, c-Jun, and Akt pathways, thus inducing the transcription of IL-6, TGF-β, and MMP, which drive cancer cell proliferation and invasion." (PMID 35625629, 2022). "The intracellular pathways involved in leptin signaling include JAK/STAT, ERK, and PI3K, culminating in increased proliferation, survival, invasion, and angiogenesis, all of which are hallmarks of cancer development." (PMID 35164764, 2022).
cancer (continued). "The inconsistent or paradoxical results assigned to leptin genetics and various cancer types, including CRC, could reside in interfering factors such as the genetic heterogeneity of cancers, malignancy grade, clinical heterogeneity, and exposure." (PMID 35563103, 2022). "Moreover, leptin can also lead to vascular VEGF overexpression, a feature of malignant tumor development." (PMID 34751020, 2022). "There is also evidence that leptin is not a robust biomarker in males in comparison to females with the same types of cancer." (PMID 35628271, 2022). "Factors including adiponectin, leptin and others remodel the TME to supports the cancer growth." (PMID 35150338, 2022). "Hereby, we discuss in detail the oncogenic pathways that LEP, upon binding to its receptor LEPR is able to activate, thus promoting cell proliferation, migration, and angiogenesis, largely acknowledged as hallmarks of cancer." (PMID 36291602, 2022). "Similarly, 3 markers (CFD, LEP and DKK3) were downregulated both in tumour lysates and plasma from patients with cancer." (PMID 34997107, 2022). "PPARγ agonists, TZDs, induced ADP expression and secretion in a dose- and time-dependent manner in humans and rodents in vitro and in vivo and suppressed the growth, migration, and invasion of cancer cells by augmenting ADP expression and inhibiting leptin signaling." (PMID 33671547, 2021). "Unlike leptin, the effect of adiponectin on cancer cell-specific lipid metabolism and its contribution to anti-tumor effects of adiponectin are poorly understood." (PMID 33535537, 2021). "Moreover, the secretion of leptin is triggered by insulin, TNF alfa, reproductive hormones, but also by hypoxia via HIF-1, which all are involved in cancer development." (PMID 33809784, 2021). "Leptin may further contribute to tumor development and metastasis by promoting the acceleration of EMT in cancer stem cells." (PMID 34681797, 2021). "Leptin also upregulates the expression of CD63 in basophils and allows the production of type 2 cytokines such as IL-4 or IL-13, which play an important role in some types of cancer." (PMID 34202969, 2021). "The crosstalk between adipose stem cells (ASC) and cancer cells seems to be mediated through the release of several growth factors (VEGF, PDGF, TGF-β), cytokines (IL-6, Il-8, IFN-γ, TNF-a, CXCL2, CXC12), and leptin by the former." (PMID 33918733, 2021). "Leptin (LEP), a 16-kDa hormone of energy expenditure, is a balancing mediator of homeostasis by regulating acquisition and consumption of energy, which was a basic pathophysiological process in normal cells and cancer cells." (PMID 34868961, 2021). "Leptin binds to the leptin receptors on the plasma membrane to drive multiple downstream signaling cascades, such as JAK-STAT, PI3K-Akt-FoxO1, AMPK, and mTOR-S6K that involves in the cell proliferation, transformation, migration, and invasion of cancer." (PMID 34970222, 2021). "In contrast, results illustrating the negative correlation of leptin or leptin receptors with cancer progression have also been reported." (PMID 33799880, 2021). "Notably, inhibition of leptin signaling significantly reduced ABCB1 gene expression, which is well known to have high specificity for the elimination of paclitaxel from cancer cells." (PMID 32471192, 2020). "The mechanism may be related to Leptin/STAT3 signal transduction, VEGF-A, VEGFR-1 and WCAF target proteins related to cancer immune such as leptin and AKT1." (PMID 33746736, 2020). "Leptin activates multiple downstream signaling via SOCS-STAT3 transcription activation, thereby activating MAPK and AKT pathways, resulting in increased proliferation, angiogenesis and decreased apoptotic death in cancer cells." (PMID 32796696, 2020). "The different studies report that leptin promotes the expression of mesenchymal markers and a decrease in epithelial markers, in addition to promoting EMT-related processes such as cell migration and invasion and poor prognosis in patients with cancer." (PMID 33334030, 2020).
cancer (continued). "In cancer, numerous reports suggest that BMA-derived fatty acids and factors such as fatty acids binding protein 4 (FABP4) and leptin, might drive tumour progression in prostate and breast cancer." (PMID 32527062, 2020). "The finding of a significant relationship between leptin and TGF-β1 levels in our patients is consistent with previous studies that showed that leptin binds to leptin receptors on the surface of cancer cells, activates JAK/STAT3 signaling, and consequently increases TGF-β expression." (PMID 32968152, 2020). "In addition to stimulating tumor cell proliferation and invasion, leptin signaling was also reported to promote EMT and the generation of cancer stem cells." (PMID 33604295, 2020). "Leptin, IL-6, and TNF-α are proinflammatory cytokines produced by adipose tissue and that are also increased in cancer, while adiponectin protects against tumorigenesis and its serum levels are usually decreased in cancer patients." (PMID 32604970, 2020). "The expression level of each of MC4R and LEP in several types of cancer tissues did not alter significantly." (PMID 33299884, 2020). "For person neoplasm cancer status, LOC285000 and LEP could distinguish the prognosis of patients free from neoplasm, while SLC30A3 and DYNC1I1 were significant for patients with neoplasm." (PMID 32528533, 2020). "Among the pathophysiological mechanisms involved, leptin does not seem to interfere with the estrogenic pathway but seems to promote the proliferation of cancer stem cells." (PMID 31756890, 2019). "Furthermore, a subset of cancer biomarkers (CYFRA 21-1, TNFα, TRAIL, leptin and sFasL) strongly discriminated the high and low diversity/inflammation cluster groups." (PMID 31089160, 2019). "Then, we investigated whether the effects of leptin on FAK and Src activation and the enhanced migratory capabilities of cultured cancer cells were mediated by the canonical leptin-receptor signaling pathway." (PMID 31671408, 2019). "Some studies reported a relationship between metastasis-associated protein 1 (MTA1) and the regulation of Wnt1 in endothelial and cancer cells, and MTA1 might be a novel target for leptin." (PMID 31736756, 2019). "Furthermore, western blot assays suggested that the MAPK/ERK1/2 and PI3K/AKT signaling pathways were activated by leptin produced by CAFs, which demonstrated that the functions of paracrine leptin in NSCLC are as those of the serum leptin to other cancers." (PMID 31119158, 2019). "Leptin and OBR receptors have been reported to be overexpressed in numerous types of cancer." (PMID 31109060, 2019). "This phenotype was accompanied by a decrease in the leptin-induced invasive capabilities of the MDA-MB-231 cell line treated with PP2, supporting the role for Src in cell migration and invasion of cancer cells." (PMID 31671408, 2019). "In the first cluster, 100% of pairs of cancer biomarkers (36/36) exhibited positive correlation (adjusted P < 0.05) with the highest correlations between FGF2 and leptin (ρ = 0.84, P < 0.0001), FGF2 and TRAIL (ρ = 0.80, P < 0.0001) and leptin and TRAIL (ρ = 0.77, P < 0.0001)." (PMID 31089160, 2019). "Sera analysis in wild-type male mice showed a significant difference in leptin level in animals subjected to surgery that developed dysplasia and cancer compared with non-operated controls." (PMID 29662006, 2018). "Furthermore, TGFβ1 was required for leptin-mediated EMT and metastatic ability in normal epithelial and cancer cell lines of breast (MCF7, MCF10A, MDA-MB-231 and MCF10AT1)." (PMID 29682217, 2018). "In view of the many effects shown by leptin on PC chemoresistance, cancer stem cells and Notch and RBP-Jk signaling, we speculate that the inhibition of leptin signaling might be a new strategy to sensitize PC to chemotherapeutics." (PMID 30004402, 2018). "Leptin induced a greater increase in VEGF/VEGFR2 and LIF levels in cancer than in benign cells." (PMID 30510663, 2018).